CASP1 (caspase 1)
Diseases named in the same sentence as CASP1 in open-access papers (continued):
Sharing a sentence is not in itself a finding about the gene and the disease.
E. coli infection (continued). "In summary, we showed that caspase-1 inflammasome-licensed pyroptosis could drive necroptosis in a paracrine manner during pulmonary E. coli infection." (PMID 40359428, 2025). "We also measured lactate dehydrogenase (LDH) and high mobility group protein 1 (HMGB-1) levels in the BALF, both of which are released during lytic cell death, and observed significantly higher levels of LDH and HMGB-1 in the BALF of the Casp1+/+ mice after E. coli infection." (PMID 40359428, 2025). "Lactobacillus rhamnosus GR-1 suppresses ASC-dependent NLRP3 inflammasome activation and ASC-independent caspase-1 processing by inhibiting caspase-4 activation, thereby attenuating cell pyroptosis and cytokine production and thus preventing establishment of E. coli infection." (PMID 30087667, 2018). "It must be noted that ASC deficiency reduced, but did not abolish, caspase-1 processing, IL-1β and IL-18 maturation, and cell pyroptosis during E. coli infection." (PMID 30087667, 2018). "However, after 6 h of E. coli infection, caspase 1 activity was increased in LD4-PP-treated cells." (PMID 41415272, 2025). "To further elucidate the mechanism of pyroptosis induced by E. coli infection, we mined the dataset (GSE124917) in the GEO database and found that E. coli infection significantly upregulates NLRP3, caspase-1, GSDMD, and IL-1β." (PMID 37511208, 2023). "Our results showed that NLRP3, caspase-1, GSDMD, and IL-1β were significantly upregulated in response to E. coli infection, with KEGG enrichment revealing that upregulated genes were mainly concentrated in the NOD-like receptor signaling pathway." (PMID 37511208, 2023). "E. coli infection induced NOD-like receptor family member pyrin domain-containing protein 3 (NLRP3) inflammasome assembly, Caspase-1 activation, and apoptosis in MAC-T cells." (PMID 34594329, 2021). "RNA-seq analysis revealed that ZBP1 transcripts were abundant in BALF neutrophils from both Casp1+/+ and Casp1-/- mice following pulmonary E. coli infection, whereas TRIF transcripts were not detectable." (PMID 40359428, 2025). "In validation experiments, chimeric mice with nonhematopoietic caspase-1 or GSDMD knockout were protected from lung E. coli infection and exhibited decreased neutrophil death." (PMID 40359428, 2025). "Compared with WT cells, ASC deletion attenuated, but did not abolish, caspase-1 staining in response to E. coli infection and pre-incubation with L. rhamnosus GR-1." (PMID 30087667, 2018). "Thus, the decreased levels of IL-1β after E. coli infection but not as a result of S. agalactiae’s presence in the hyperglycemic placenta could be explained by the inhibition of the inflammasome complex formation or caspase 1 activation." (PMID 36982317, 2023).
endothelial dysfunction (17 papers, 2017 to 2025). In vascular diseases, endothelial dysfunction is a systemic pathological state of the endothelium (the inner lining of blood vessels) and can be broadly defined as an imbalance between vasodilating and vasoconstricting substances produced by (or acting on) the endothelium. "These EVs overexpress transcripts for proteins linked to vascular injury, apoptosis, and inflammation, including endothelin-1 (EDN1) and caspase-1 (CASP1), both of which contribute to endothelial dysfunction and heightened cardiovascular risk." (PMID 40725065, 2025). "Moreover, ROS are also responsible for pathological processes in the vasculature, causing endothelial dysfunction through the interruption of vasoprotective pathways such as NO signaling, as well as triggering inflammasome and cytokines such as IL-1β and IL-8 via activation of caspase-1." (PMID 36839268, 2023). "Previous vascular functional studies confirmed that NLRP3 inflammasome plays a pivotal role in the regulation of endothelial dysfunction by activation of caspase-1, IL-1β, and IL-18 in metabolic disease models." (PMID 34326395, 2021). "Canonical NALP3 inflammasome activation is a caspase-1 medicated process, resulting in the secretion of IL-18 and IL-1β which lead to endothelial dysfunction." (PMID 30186184, 2018). "To investigate whether NLRP3 inflammasome is associated with the activation of caspase-1 and endothelial dysfunction in rickettsial infection, we determined the effect of the selective NLRP3 inhibitor MCC950 on the expression levels of active caspase-1." (PMID 39679710, 2025). "Therefore, our study is the first to demonstrate that Sil improves endothelial dysfunction by blocking the NLRP3/caspase-1 pyroptosis pathway." (PMID 37636019, 2023). "Following activation of the NALP3 inflammasome, procaspase-1 is self-cleaved to become active caspase-1 and further turn pro-IL-1β to IL-1β, which may lead to endothelial dysfunction." (PMID 30186184, 2018). "The results of this study indicate that Sil can decrease the expression of IL-18, NLRP3, caspase-1, and GSDMD and increase the expression of eNOS to inhibit inflammatory reaction and improve endothelial dysfunction." (PMID 37636019, 2023). "In order to delineate the pathogenesis of MDS-related endothelial dysfunction suggested by the prognostic impact of EASIX, we measured serum levels of S100A9, IL1β and IL18 (both activated by caspase 1 from pro-cytokines)." (PMID 31712595, 2019).
heart failure (17 papers, 2014 to 2026). Inability of the heart to pump blood at an adequate rate to meet tissue metabolic requirements. "Interleukin-1 converting enzyme/caspase-1 is a proinflammatory caspase that have been implicated in the pathogenesis of cardiovascular disorders, including heart failure and cardiac ischemia." (PMID 38534442, 2024). "An IL-1β-independent role for caspase-1 in cardiomyocyte cell death and heart failure has emerged but the mechanisms underlying these effects are incompletely understood." (PMID 25501827, 2014). "This study showed the increased secretion of IL-1β and IL-18 when DUOX1 was overexpressed in AC16 cells, suggesting that the caspase-1-dependent pyroptosis in heart failure was triggered by the upregulation of DUOX1." (PMID 38750444, 2024). "It is also worth noting that the caspase-1 downstream inflammatory cytokines, IL-1β and IL-18, accelerate the transition from cardiac remodeling to heart failure and thus are expected to be potential drug targets for heart failure." (PMID 33842546, 2021). "Inhibition of GATA4 – a cardiomyocyte survival factor – by caspase-1 is consistent with the reported involvement of caspase-1 in myocyte cell death and heart failure." (PMID 25501827, 2014). "Increased expression of caspase-1 has been demonstrated in murine and human adult heart failure." (PMID 41231039, 2025). "As expected, we found that caspase-1 overexpression aggravated the activation of IL-1β and IL-18 in Re-TAC 4W mice, recapitulating that HP attenuates cardiac hypertrophy and regresses heart failure through downregulation of the inflammatory cascade of caspase-1." (PMID 33842546, 2021). "Early intervention of caspase-1 may drive a promising strategy on regression of cardiac hypertrophy and heart failure." (PMID 33842546, 2021). "In the heart failure group, NLRP3, TXNIP, Caspase-1, and IL-1β protein expressions were up-regulated, and aerobic exercise and SKQ1 down-regulated NLRP3, TXNIP, Caspase-1, and IL-1β protein expressions." (PMID 40076760, 2025). "TAC promoted the development of heart failure, and cardiac fibrosis and increased the NLRP3, gasdermin D, ASC, cleaved caspase-1, p-NFκB, IL-1β, and IL-18 levels in myocardial tissue in mice." (PMID 36320147, 2022). "Aortic banding triggered the development of heart failure, cardiac hypertrophy, cardiomyocyte hypertrophy, and cardiac fibrosis, and increased NLRP3, NFκB, ASC, IL-1β, cleaved caspase-1 expression, and inflammatory cell infiltration." (PMID 36320147, 2022). "Activation of TLR4, caspase-1, IL-1β, and mast cells are also known to increase myocarditis and promote remodeling, fibrosis, and DCM in CVB3 myocarditis in male mice suggesting that BPA exposure could increase the risk of progression from myocarditis to DCM and heart failure in women." (PMID 31551929, 2019). "Furthermore, in rats with ISO-induced heart failure, pyroptosis and inflammatory responses were exacerbated, including increases in GSDMD, cleaved GSDMD, caspase 1, cleaved caspase 1, and IL-1β by 1.56- (P<0.05), 2.87- (P<0.001), 2.14- (P<0.01), 2.67- (P<0.01), and 7.11-fold (P<0.001), respectively." (PMID 36327230, 2022).
ulcerative colitis (17 papers, 2019 to 2025). An inflammatory bowel disease involving the mucosal surface of the large intestine and rectum. "1,25(OH)2D3 treatment also inhibited caspase-1 activation and IL1β secretion in an ulcerative colitis model." (PMID 37867510, 2023). "The strong green fluorescence from the cytosolic regions of the colon tissues stained with anti-Caspase-1 antibody from ulcerative colitis model mice clearly reveals high expression of Caspase-1 (Mean Fl." (PMID 37328528, 2023). "CASP1, encoding caspase 1, is a key component of NLRP3 inflammasomes and is positively related to active ulcerative colitis." (PMID 36619896, 2022). "Pyroptosis, a highly inflammatory form of lytic programmed cell death, with initiation via activation of caspase family, including caspase-1, caspase-4, caspase-5, and caspase-11, can be triggered by various diseases, such as ulcerative colitis." (PMID 35008842, 2021). "Additionally, NLRP3 inflammasome has been investigated relatively to having a role in the pathogenesis of ulcerative colitis, as it is responsible for activating the expression of caspase-1, producing IL-1β and IL-18 and starting the inflammatory process." (PMID 35745756, 2022). "In ulcerative colitis mice model, the abundance of Alistipes is increased and the expressions of NLRP3 and caspase-1 are elevated." (PMID 40104594, 2025). "For studying how NEK7 affected the pyroptosis in IBD, we first examined the mRNA expression and protein levels of NEK7, as well as key factors in pyroptosis, including Caspase-1, NLRP3, and GSDMD, in control and ulcerative colitis tissues in IBD patients." (PMID 31787755, 2019). "The mRNA expression of NEK7, Caspase-1, NLRP3, and GSDMD showed to be remarkably increased in ulcerative colitis tissue samples than that in control tissues." (PMID 31787755, 2019).
cardiac hypertrophy (16 papers, 2018 to 2024). "Our findings indicate that caspase-1-dependent pyroptosis contributes to the pathological processes associated with myocardial hypertrophy." (PMID 39553724, 2024). "The Studies also reported that elevated mRNA of NLRP3 and enhanced cleavage of caspase-1 were observed along with cardiac hypertrophy and ventricular dilatation in calcineurin transgene (CNTg) mice, an established mouse model for chronic heart failure." (PMID 38750444, 2024). "Although cardiac hypertrophy is observed in caspase-1 knockout mice subjected to renal ischemia/reperfusion, the role of caspase-1 deletion in the mouse heart has not been fully investigated." (PMID 38534442, 2024). "Caspase-1 inhibitor, VX-765, played an inhibitory role in SiNPs-induced pyroptosis and the development of cardiac hypertrophy." (PMID 38333413, 2024). "In vivo andex vivo models of cardiac hypertrophy have demonstrated a significantupregulation in caspase-1 and IL-1β expression." (PMID 39484135, 2024). "Caspase-1 is an essential element for maintaining cardiac heath, and eliminating it can result in cardiac hypertrophy and increased vulnerability to oxidative stress." (PMID 38534442, 2024). "Cardiac hypertrophy significantly increased the proportion of apoptotic cells and upregulated apoptosis-associated speck-like protein containing a CARD (ASC), caspase-1, and gasdermin D (GSDMD)." (PMID 39553724, 2024). "Its activation contributes to the development of cardiac hypertrophy by cleaving pro-caspase-1 and promoting the release of proinflammatory cytokine IL-β." (PMID 35731090, 2022). "Pyrroloquinoline quinone inhibited ROS and NF-κB activation inhibited NLRP3 inflammasome and Caspase-1, IL-1β and IL-18 expression, and improved myocardial hypertrophy and cardiac fibrosis." (PMID 35509275, 2022). "The decrease in the level of ROS causes the NLRP3 inflammasome to fail to assemble and activate the caspase-1 signaling pathway, thereby inhibiting pyroptosis and cardiac hypertrophy." (PMID 35647057, 2022). "Cardiac hypertrophy significantly increased the percentage of apoptotic cells and upregulated IL-1β, cleaved caspase-1, and GSDMD-N that lie downstream of the NLRP3 inflammasome." (PMID 33723236, 2021). "Our findings indicated that NLRP3/caspase-1-dependent pyroptosis has a pathological role in myocardial hypertrophy." (PMID 33723236, 2021). "Collectively, this study revealed a previously unrecognized involvement of caspase-1 in cardiac HP by regulation of IL-1β and IL-18 and shed light on caspase-1 as an antecedent indicator and target for cardiac hypertrophy." (PMID 33842546, 2021). "Targeted inhibition of NLRP3 by CRID3 and gene silencing blocked caspase-1-dependent pyroptosis in cardiomyocytes and alleviated the signs of cardiac hypertrophy." (PMID 33723236, 2021). "Although cardiac hypertrophy is observed in caspase-1 knockout mice subjected to renal ischemia/reperfusion, caspase-1 is confirmed to induce inflammatory infiltration during long-term cardiac pressure overload." (PMID 33842546, 2021). "The results showed that caspase-1 and IL-1β expression levels were significantly up-regulated during cardiac hypertrophy." (PMID 29440460, 2018). "In conclusion, our results provide a novel evidence that caspase-1 mediated pyroptosis is involved in cardiac hypertrophy, and the inhibition of caspase-1 will offer a therapeutic potential against cardiac hypertrophy." (PMID 29440460, 2018). "TAC was used to establish a mice model of cardiac hypertrophy and cleaved caspase-1 and IL-1β expression levels were detected." (PMID 29440460, 2018). "The present study aimed to explore the possible role of caspase-1 in pathogenesis of cardiac hypertrophy." (PMID 29440460, 2018). "The aim of the present work was to investigate the effect of cleaved caspase-1-mediated pyroptosis in cardiac hypertrophy." (PMID 29440460, 2018).
cardiac hypertrophy (continued). "In conclusion, our results provide a novel evidence that caspase-1-mediated pyroptosis plays an important role in cardiac hypertrophy, and the inhibition of caspase-1 will offer a therapeutic potential against cardiac hypertrophy." (PMID 29440460, 2018). "We established cardiac hypertrophy models both in vivo and in vitro to detect the expression of caspase-1 and interleukin-1β (IL-1β)." (PMID 29440460, 2018). "Caspase-1 isinvolved in cardiac hypertrophy by regulating IL-1β and IL-18 expression." (PMID 39484135, 2024). "Meanwhile, silica nanoparticles (SiNPs) exposure is correlated with adverse cardiovascular effects, literature suggested SiNPs could trigger pyroptosis and cardiac hypertrophy via ROS/NLRP3/Caspase-1 signaling pathway." (PMID 35509275, 2022). "In vitro and in vivo models of cardiac hypertrophy, the expression levels of pyroptosis-related factors were significantly increased, downregulation of Caspase-1 and IL-1β expression by Caspase-1 inhibitors attenuates angiotensin II (Ang II) -induced cardiac hypertrophy." (PMID 35509275, 2022). "Subsequently, we observed the effect of caspase-1 inhibitor on cardiac hypertrophy." (PMID 29440460, 2018). "Subsequently, caspase-1 inhibitor was co-administered with angiotensin II (Ang II) in cardiomyocytes to observe whether it could attenuate cardiac hypertrophy." (PMID 29440460, 2018). "Hence, inhibiting caspase-1 is a potential therapeutic strategy formanaging cardiac hypertrophy." (PMID 39484135, 2024). "Therefore, caspase-1 possibly regulates MAPKs to modulate cardiac hypertrophy." (PMID 38534442, 2024). "Moreover, although it is recently found that caspase-1 is activated in mice after aortic banding and regulates angiotensin II-induced cardiac hypertrophy by cleavage of IL-1β, whether caspase-1 plays a role in HP requires further investigation." (PMID 33842546, 2021). "However, little was known about the role of caspase-1-induced pyroptosis in cardiac hypertrophy." (PMID 29440460, 2018). "Therefore, inhibition of caspase-1 may be a new strategy for prevention and treatment of cardiac hypertrophy." (PMID 29440460, 2018). "However, the exact role of caspase-1 in cardiac hypertrophy is yet to be discovered." (PMID 29440460, 2018). "The increase in pyroptosis in myocardial hypertrophy was accompanied by enhanced regulation of NLRP3, caspase-1, ASC, and GSDMD." (PMID 39553724, 2024). "We established in vivo and in vitro models of cardiac hypertrophy via TAC and Ang-II treatment, respectively, and observed a significant increase in pyroptotic cells, along with upregulation in IL-1β, cleaved caspase-1, and GSDMD-N." (PMID 33723236, 2021). "A mouse model of induced myocardial hypertrophy confirmed a significant increase in the expression of activated caspase-1, IL-1β, and N-GSDMD in the myocardium, demonstrating the importance of pyroptosis in the development of HF based on myocardial hypertrophy." (PMID 38886277, 2024). "In addition, this experimental model showed that the inhibition of caspase-1 or NLRP3 reduced the severity of pyroptosis, resulting in less myocardial hypertrophy and less severe HF." (PMID 38886277, 2024). "Silica nanoparticles lead to cardiac hypertrophy and pyroptosis by the NLRP3/ROS/caspase-1 pathway." (PMID 38730417, 2024).